DOCK2 (dedicator of cytokinesis 2)
Diseases named in the same sentence as DOCK2 in open-access papers (continued):
Sharing a sentence is not in itself a finding about the gene and the disease.
myeloid leukemia (1 paper, 2020). A clonal proliferation of myeloid cells and their precursors in the bone marrow, peripheral blood, and spleen. "Our data suggest an important contribution by RASSF2 in cooperation with DOCK2 to this process in myeloid leukemia cells, which we reveal to have important consequences in AML." (PMID 32029705, 2020).
myocarditis (1 paper, 2022). Myocarditis is a condition that is characterized by inflammation of the heart muscle (myocardium). "Analysis by the GSE35182 and GSE53607 databases showed that DOCK2 was significantly upregulated in myocarditis." (PMID 36250020, 2022). "The study revealed a correlation between miR-16 and DOCK2, with miR-16 expression significantly down-regulated in LPS-induced myocarditis." (PMID 36250020, 2022). "In conclusion, DOCK2 is involved in the development and progression of myocarditis by regulating the expression and secretion of inflammatory factors." (PMID 36250020, 2022).
osteoarthritis (1 paper, 2018). A noninflammatory degenerative joint disease occurring chiefly in older persons, characterized by degeneration of the articular cartilage, hypertrophy of bone at the margins and changes in the synovial membrane. "Both DOCK2 and ROR2 represent potential drug targets for therapies targeting the biochemical aspect of ACLR and associated osteoarthritis." (PMID 29940858, 2018).
osteosarcoma (1 paper, 2021). A usually aggressive malignant bone-forming mesenchymal neoplasm, predominantly affecting adolescents and young adults. "Distinct from the identification of ABR, PREX1 and DOCK2 in non-cancer cells, DOCK4 identification was initially reported in osteosarcoma cells, in which DOCK4 was deleted during tumor progression." (PMID 34783629, 2021).
peritonitis (1 paper, 2023). Inflammation of the peritoneum (tissue that lines the abdominal wall and covers most of the organs in the abdomen). "Finally, we showed that neutrophil recruitment is impaired in Dock2-deficient mice during sterile peritonitis, which showed that this GEF is an important regulator of neutrophil migration not only in vitro but also in vivo." (PMID 37383235, 2023). "Finally, we subjected Dock2–/– mice to intraperitoneal challenge with thioglycollate (TGC) to induce sterile peritonitis and assessed neutrophil recruitment after 3 h." (PMID 37383235, 2023).
psoriasis (1 paper, 2025). An autoimmune condition characterized by red, well-delineated plaques with silvery scales that are usually on the extensor surfaces and scalp. "Notably, Sult2b1−/−Dock2−/− mice exhibited significant recovery of psoriasis-like phenotypes and neutrophil infiltration in the skin compared to Sult2b1−/−Dock2+/+ mice, suggesting that CS alleviates IMQ-induced psoriatic dermatitis by suppressing DOCK2 function." (PMID 41181147, 2025).
renal fibrosis (1 paper, 2023). A final common manifestation of a wide variety of chronic kidney diseases characterized by glomerulosclerosis and tubulointerstitial fibrosis. "DOCK2, SLC1A3, SOX9, and TARP were identified as potential diagnostic genes for renal fibrosis, and the most relevant immune cells were identified." (PMID 37359552, 2023). "The expression levels of DOCK2, SLC1A3, SOX9, and TARP were higher in the renal fibrosis group than in the control group." (PMID 37359552, 2023). "Four candidate genes namely DOCK2, SLC1A3, SOX9 and TARP were identified as biomarkers of renal fibrosis, with the area under the ROC curve (AUC) values higher than 0.75." (PMID 37359552, 2023). "We also found the expression of DOCK2, SLC1A3, SOX9, and TARP were higher in blood of renal fibrosis patients than healthy individuals." (PMID 37359552, 2023).
restrictive lung disease (1 paper, 2022). "DOCK2 can promote pleural fibrosis by modulating mesothelial to mesenchymal transition (MesoMT), which results in restrictive lung disease." (PMID 36250020, 2022).
synovitis (1 paper, 2018). Inflammation of a synovial membrane. "A locus on Chr4 associated with both ACLR and TPA resides within DOCK2, a gene that has been shown to promote immune cell migration and invasion in synovitis, an important predictor of ACLR." (PMID 29940858, 2018).
thymoma (1 paper, 2012). A neoplasm arising from the epithelial cells of the thymus. "We found that unlike wild-type DOCK2, DOCK2 mutant lacking lobe A failed to restore motility and polarity when expressed in thymoma cells and primary T cells lacking endogenous expression of DOCK2." (PMID 23050005, 2012).
triple-negative breast carcinoma (1 paper, 2020). An invasive breast carcinoma which is negative for expression of estrogen receptor (ER), progesterone receptor (PR), and human epidermal growth factor receptor 2 (HER2). "Based on the analysis of the bc-GenExMiner v4.4 database, CD1B, THY1 and DOCK2 were found to affect the metastatic recurrence of triple-negative breast cancer." (PMID 32867782, 2020).
cancer (19 papers, 2013 to 2025). A tumor composed of atypical neoplastic, often pleomorphic cells that invade other tissues. "Consistent with our previous findings in cancer models, we found γδ T cells were more abundant in Dock2 deficient than control colons." (PMID 39242821, 2024). "The results revealed that the mutation frequency of DOCK2 was relatively higher than that in non-cancer control subjects, and patients with DOCK2 mutations had a low survival rate and a poor prognosis compared with the DOCK2-wild group." (PMID 35620462, 2022). "This defective recognition of cancer cells together with the upregulation of IFNγ in DOCK-2 deficient T cells may result in tumour promotion via increased expression of IDO1." (PMID 39242821, 2024). "Therefore, IDO1 inhibitors may be particularly beneficial to patients with IBD and at high risk of developing cancer, in particular those carrying previously identified high risk DOCK2 mutations." (PMID 39242821, 2024). "CPYPP, a DOCK (dedicator of cytokinesis) inhibitor known for its anti-cancer effects by disrupting the interaction between DOCK2 and Rac1, as well as CsA and curcumin, induced significant cytoplasmic vacuolization." (PMID 38858714, 2024). "Although AURKA and DOCK2 have been extensively reported to be closely related to cell proliferation and migration of cancer cells, the function of these two molecules in WJ-MSCs has not yet been studied extensively." (PMID 35450345, 2022). "Studies show that NSCLC patients with higher lymph node metastasis or cancer stage typically have lower expression of DOCK2." (PMID 36250020, 2022). "We herein show that cancer-derived cholesterol sulfate (CS), a lipid product of the sulfotransferase SULT2B1b, acts as a DOCK2 inhibitor and prevents tumor infiltration by effector T cells." (PMID 35094065, 2022). "Many studies have shown that dedicator of cytokinesis 2 (DOCK2) has a crucial role as a prognostic factor in various cancers." (PMID 35620462, 2022). "Dedicator of cytokinesis 2 (DOCK2), originally known as KIAA0209, encodes CDM protein and has been discovered to be linked with a prognostic factor in various cancers." (PMID 35620462, 2022). "First, The Cancer Genome Atlas (TCGA) and the International Cancer Genome Consortium (ICGC) cohorts were utilized to identify the mutation frequency of DOCK2." (PMID 35620462, 2022). "Taken together, these results suggested that hnRNP A2B1 regulated the pre-mRNA splicing of pro-apoptosis genes (DAPK1, SYT7, and RNF128) and anti-apoptosis genes (EIF3H, TPPP3, and DOCK2), thus leading to the suppression of apoptosis of cancer stem cells." (PMID 33509274, 2021). "DOCK2 has the functions of activating small G proteins such as Rac1/2 and subsequently activates downstream pathways which involved in survival, proliferation and migration of cancer." (PMID 33259129, 2021). "In this context, KCNAB2, H2AFY, DOCK2 and GSTM1 in our signature significant high expression in high‐risk group compare to low‐risk group and related to poor prognosis, and all genes except KCNAB2 in signature have been reported to be involved in cancer." (PMID 33259129, 2021). "Several studies revealed that DOCK2 is critical in the development of various inflammatory diseases and cancers; however, its role in REPL is unknown." (PMID 32401299, 2020). "DOCK2 is an atypical guanine nucleotide exchange factor that has been shown to be involved in the regulation of cell migration and proliferation through the small G protein Rac in various cancer types." (PMID 30866497, 2019). "Besides, the frequency of TPR|FOXA3 and ABCA 7|DOCK2 were larger than 0.1 in more than 10 cancers." (PMID 36139377, 2022). "Variations in angiotensin-converting enzyme 2 (ACE2), transmembrane protease serine 2, A disintegrin and metalloprotease 17 (ADAM17), and Dedicator of cytokinesis 2 (DOCK2) levels, influenced by cancer types, differ among populations." (PMID 39946554, 2025).
cancer (continued). "As reported, TPPP3, DOCK2, and EIF3H act as oncogenes by suppressing apoptosis of cancer cells, while RNF128, DAPK1, and SYT7 function as tumor suppressors by promoting apoptosis of many types of cancer cells." (PMID 33509274, 2021). "Hence, the downregulation of ABR, PREX1, DOCK2, and DOCK4 promotes cancer development and leads to a poor prognosis by activating MYC and DNA repair signaling pathways in NSCLC, and further in vitro and in vivo studies are necessary to further confirm their association." (PMID 34783629, 2021). "In addition, NSCLC subgroups with higher nodal metastasis levels or cancer stages generally have lower median expression of ABR, PREX1, DOCK2, and DOCK4, whereas statistical significance for the comparison among these subgroups remains to be verified with a larger number of samples." (PMID 34783629, 2021).
tumor (17 papers, 2010 to 2025). "Multivariate linear regression analysis identified SNPs in 11 genes (Sepsecs, Rhobtb1, Tsen15, Abcc3, Arid5b, Tnr, Dock2, Tti1, Fam81a, Stx6, and Oxr1) that were independently associated with the tumour multiplicities." (PMID 39067134, 2024). "This phenotype was driven by increased IFNγ-production in T cell populations, which infiltrated Dock2-deficient tumours, promoting IDO1 expression in tumour epithelial cells." (PMID 39242821, 2024). "Together, this suggests an induction of IFNγ signalling in the tumour epithelium of Dock2 deficient mice." (PMID 39242821, 2024). "We also found that DOCK2 mutation and/or low DOCK2 expression correlates poor prognosis in these patients, further supporting a tumour suppressor role for this protein." (PMID 39242821, 2024). "We further validated this upregulation at protein level observing upregulation of IDO1 protein in Dock2 deficient tumours by IHC and Western blot." (PMID 39242821, 2024). "Gene ontology (GO) analysis of our dataset identified enrichment of numerous immune related pathways as being activated in Dock2 deficient tumours." (PMID 39242821, 2024). "To further test the functional significance of elevated IDO1 expression and tryptophan metabolism in Dock2 deficient tumours we next examined the effect of IDO1 inhibition on tumourigenesis." (PMID 39242821, 2024). "We pooled all 20 genes (Stx6, Ramp1, Traf3ip1, Nckap5, Pfkfb2, Trmt1l, Rprd1b, Rer1, Sepsecs, Rhobtb1, Tsen15, Abcc3, Arid5b, Tnr, Dock2, Tti1, Fam81a, Oxr1, Plxna2 and Tbc1d31) together as the mouse tumour susceptibility gene signature (mTSGS)." (PMID 39067134, 2024). "We find this increased tumourigenesis is associated with CD3 + T cell infiltration, increased interferon gamma signalling, elevated expression of the IFNγ target IDO1 and increased tryptophan metabolism in Dock2-deficient tumours." (PMID 39242821, 2024). "Thus, the responsiveness of Dock2 deficient and normal tumour organoids to IFNγ stimulation is broadly similar." (PMID 39242821, 2024). "We next investigated whether the increased IDO1 observed in Dock2 deficient tumours impacted on tryptophan metabolism." (PMID 39242821, 2024). "Infiltrating Vγ1 γδ T cells have previously been identified as a potential source of IFNγ in tumours suggesting this immune cell population may be partly mediating IFNγ signalling in Dock2 deficient tumours." (PMID 39242821, 2024). "Together, this suggests the increased IFNγ response observed in vivo may be due to elevated infiltration of IFNγ producing cells in Dock2 deficient tumours." (PMID 39242821, 2024). "We identified numerous changes in metabolite levels in Dock2 deficient tumours." (PMID 39242821, 2024). "Together, this supports the hypothesis that increased IFNγ production, from non-cell autonomous sources, is driving elevated IDO1 expression in tumour epithelial cells in Dock2 deficient mice." (PMID 39242821, 2024). "After clarifying the characteristic genes that are most related to DOCK2 mutation, the risk score was developed, which played an excellent role in predicting the status of survival, tumor mutation burden (TMB), and microsatellite instability (MSI) in DOCK2 mutant patients." (PMID 35620462, 2022). "Cholesterol sulfate, synthesized by sulfotransferase 2B1 (SULT2B1) in tumor cells, is secreted to suppress dedicator of cytokinesis protein 2 (DOCK2) enzymatic activity in T cells, leading to CD8+ T cell exhaustion." (PMID 40270603, 2025).
tumor (continued). "To define in better detail the cellular compartment expressing IDO1 we co-stained Vil Apc Dock2 tumour tissue for epithelial and immune cell markers alongside IDO1." (PMID 39242821, 2024). "Further investigations of different T cell subtypes demonstrated that whilst CD4+ and CD8 + T cell infiltration was the same between groups, there were more γδ T cells in Vil Apc Dock2 tumours than control tumours." (PMID 39242821, 2024). "To identify potential molecular mechanisms mediating increased tumourigenesis following Dock2 deletion we carried out RNAseq on 5 vs 9 colonic tumours dissected from Vil Apc and Vil Apc Dock2 mice." (PMID 39242821, 2024). "Dock2 was the most downregulated gene, with a logFC of −2.89 and an adjusted p value = 8.87 × 10−35, in line with the minimal Dock2 expression observed in the Vil Apc Dock2 tumours." (PMID 39242821, 2024). "To identify metabolic differences between Vil Apc and Vil Apc Dock2 tumours, we performed liquid chromatography mass spectrometry (LC-MS)." (PMID 39242821, 2024). "Collectively, these results indicate that CS production by tumor cells dampens anti-tumor T-cell responses by inhibiting the function of DOCK2." (PMID 35094065, 2022). "The downregulation of PREX1 and DOCK2 were significantly correlated with earlier tumor progression in LUSC and LUAD patients." (PMID 34783629, 2021). "In mPCa patients with low tumor volume, methylated ctDNA was detected in a total of 32.3% (10/31) of the patients, with 6/31 (19.4%) patients positive for DOCK2, 9/31 (29.0%) positive for HAPLN3, and 3/12 (25.0%) positive for FBXO30." (PMID 32486483, 2020). "In de novo mPCa patients, we detected methylated ctDNA in 32.3% of the patients with low tumor volume and in 89.3% of patients with high tumor volume using the DOCK2, HAPLN3, and FBXO30 assays (positive for at least one assay)." (PMID 32486483, 2020). "Specificity/sensitivity for high tumor volume was 81%/71% for DOCK2, 71%/89% for HAPLN3, and 75%/77% for FBXO30." (PMID 32486483, 2020). "In contrast, methylated ctDNA was detected in 89.2% (25/28) of mPCa patients with high tumor volume; 20/28 (71.4%) patients positive for DOCK2, 25/28 (89.2%) positive for HAPLN3, and 13/17 (76.5%) positive for FBXO30." (PMID 32486483, 2020). "Similar to other DOCK family members such as DOCK2—which exhibits either tumor-suppressive or tumor-promoting roles depending on the specific tumor context and immune microenvironment—DOCK4 is involved in diverse signaling pathways in LUAD, including MYC signaling and DNA repair." (PMID 40529490, 2025). "Interestingly, we did not observe differences in the levels of kynurenine but the downstream metabolite xanthurenate was elevated in Vil Apc Dock2 tumours suggesting a rapid conversion of kynurenine via this pathway." (PMID 39242821, 2024). "As DOCK2 primarily functions as an immune modulator we examined whether immune cell dysregulation might be responsible for the observed IFNγ stimulation and thus impacting tumour formation in Dock2 deleted mice." (PMID 39242821, 2024). "Dock2-deficient tumours displayed increased levels of IFNγ-associated genes, including the tryptophan metabolising, immune modulatory enzyme, IDO1, when compared to Dock2-proficient tumours." (PMID 39242821, 2024). "Multivariate analyses flagged SNPs in 20 genes (Stx6, Ramp1, Traf3ip1, Nckap5, Pfkfb2, Trmt1l, Rprd1b, Rer1, Sepsecs, Rhobtb1, Tsen15, Abcc3, Arid5b, Tnr, Dock2, Tti1, Fam81a, Oxr1, Plxna2, and Tbc1d31) independently tied to various tumour characteristics, designated as a mTSGS." (PMID 39067134, 2024). "To date, DOCK2 has been closely related to neoplastic diseases." (PMID 36250020, 2022).